NEFL (neurofilament light chain)
Diseases named in the same sentence as NEFL in open-access papers (continued):
Sharing a sentence is not in itself a finding about the gene and the disease.
prion disease (36 papers, 2009 to 2026). A transmissible disease that is caused by a protein that is able to induce abnormal folding of normal cellular proteins, leading to characteristic spongiform brain changes, which are associated with neuronal loss without an inflammatory response. "Emerging data on the diagnostic utility of neurofilament light chain (NfL), (a surrogate biomarker of neuroaxonal degeneration), have indicated a possible role as a highly sensitive, supportive third-level biomarker in prion disease cases with atypical clinical and laboratory findings." (PMID 35614914, 2022). "Blood neurofilament light chain (NfL) is a promising marker in prion diseases, particularly for early screening, prognosis, and presymptomatic monitoring." (PMID 41286547, 2025). "There were also no consistent differences in serum neurofilament light-chain (NfL) levels, which is a sentinel neurodegeneration biomarker in prion disease." (PMID 41186731, 2025). "Neurofilament light chain (NFL), the main components of the neuronal cytoskeleton, have shown some diagnostic potential in human prion diseases and other neurogenerative diseases." (PMID 33767334, 2021). "CSF biomarkers that have been studied in prion disease primarily include 14-3-3, total tau, phosphorylated tau, neurofilament light chain, neuron-specific enolase, alpha-synuclein and to a lesser extent, S100B and thymosin B4." (PMID 33925126, 2021). "In this study, we employed a fully automated multiplex ELISA (Ella®) to measure the concentrations of 14-3-3 protein, total tau protein, and neurofilament light chain (NF-L) in cerebrospinal fluid (CSF) and serum samples from patients with prion disease and analyzed their link to disease prognosis." (PMID 39858404, 2024). "Using ultrasensitive immuno-assays, we measured tau and neurofilament light chain (NfL) protein concentrations in 709 plasma samples taken from 377 individuals with prion disease during a 12 year prospective clinical study, alongside healthy and neurological control groups." (PMID 33674752, 2021). "Other biomarkers like the 14-3-3 protein, neurofilament light chain protein (NfL), and α-synuclein also show a high sensitivity up to the 9th percentile, but these proteins lack specificity for prion diseases and also might not show elevated levels during the disease course." (PMID 37854584, 2023).
progressive supranuclear palsy (33 papers, 2017 to 2025). A rare late-onset neurodegenerative disease characterized by supranuclear gaze palsy, postural instability, progressive rigidity, and mild dementia. "And several meta-analysis are already done showing that neurofilament light chain protein (NF-L) concentrations in CSF are significantly increased in MSA and progressive supranuclear palsy (PSP) compared to PD." (PMID 34158872, 2021).
cardiac arrest (32 papers, 2013 to 2025). Cessation of breathing and/or cardiac function. "A recent study found serum neurofilament light chain (NfL) levels to be strongly associated with poor neurological outcome in patients after cardiac arrest." (PMID 33472689, 2021). "Indeed, recent findings demonstrated that the deletion of indoleamine 2,3-dioxygen was linked to reduced neurofilament light chain (NFL), a biomarker of brain injury, in mouse models of cardiac arrest." (PMID 40285920, 2025). "Neurofilament light chain (NfL) is a novel biomarker for the assessment of neurological function after cardiac arrest (CA)." (PMID 37713399, 2023). "In addition to NSE and S100B, several emerging neurobiomarkers—such as neurofilament light chain (NfL), Tau, and glial fibrillary acidic protein (GFAP)—have shown promise for outcome prediction after cardiac arrest." (PMID 40759951, 2025).
cerebrovascular disease (32 papers, 2008 to 2026). "CSF neurofilament light chain (NfL) is a marker of degeneration of myelinated axons and is increased in neurodegenerative, neuroinflammatory, traumatic and cerebrovascular disorders." (PMID 35164790, 2022). "Neurofilament light chain (NfL), a neuronal cytoplasmic protein highly expressed in large myelinated axons is a well-known marker in a variety of neurological disorders, including inflammatory, neurodegenerative, traumatic and cerebrovascular diseases but it is rather unspecific." (PMID 33584195, 2021).
delirium (31 papers, 2020 to 2026). A disorder characterized by confusion; inattentiveness; disorientation; illusions; hallucinations; agitation; and in some instances autonomic nervous system overactivity. "The association between cell-free DNA and neurofilament light chain suggest simultaneous release of cell-free DNA and neuronal damage during delirium." (PMID 39737468, 2025). "Among CNS injury markers, S100β and neurofilament light chain (NfL) demonstrated the most consistent associations with delirium presence and severity, supporting a role for astrocytic and axonal injury in delirium pathogenesis." (PMID 40889075, 2025). "To explore the pathophysiological relevance of the KP to delirium and outcomes for hip-fracture patients, we also investigated the association between KP metabolites and the neuronal damage marker neurofilament light chain (NfL) and 1-year mortality." (PMID 36409557, 2023). "In this cross-sectional study, we aimed to investigate whether cell-free DNA and markers of neutrophil extracellular traps in serum and CSF were associated with delirium and neuronal damage, assessed by neurofilament light chain." (PMID 39737468, 2025). "This information is supported by recently published data that demonstrated the causal association of QA with neuronal damage marker, neurofilament light chain protein (NfL) in the cerebrospinal fluid (CSF) of patients with delirium." (PMID 36982655, 2023). "Serum biomarkers such as S100β and neurofilament light chain show potential for illuminating the pathophysiology of ICU delirium, particularly astrocytic and axonal injury, but current evidence is limited by methodological inconsistencies and a lack of replication." (PMID 40889075, 2025). "Our prior studies have revealed elevated tau, neurofilament light chain, and TDP-43 on postoperative day 1 in subjects who develop postoperative delirium suggesting links between cognitive changes and markers of neurodamage." (PMID 41354326, 2025). "Neurofilament-Light chain (NfL) and Glial Fibrillary Acidic Protein (GFAP) are promising blood-based markers for neurodegenerative diseases and potential candidates for delirium." (PMID 40354379, 2025).
hippocampal atrophy (29 papers, 2016 to 2026). "In a prospective multicenter study (DELCODE) involving 457 participants across the AD continuum, we analyzed plasma phospho-tau 181 (p181) and neurofilament light chain (NfL) and assessed their association with longitudinal cognition, hippocampal atrophy, and AD clinical stage transition." (PMID 40247130, 2025). "Markers of neurodegeneration include CSF total tau (t-tau), CSF neurofilament light chain (NfL), and hippocampal atrophy and/or cortical thinning determined by magnetic resonance imaging." (PMID 39200300, 2024). "While the N component of the AT(N) framework currently focuses on markers such as hippocampal atrophy and CSF neurofilament light chain, our work suggests that axonal degeneration may play a pivotal role in early disease stages, before significant cortical atrophy becomes evident." (PMID 40832377, 2025).
Ataxia (28 papers, 2018 to 2025). Ataxia refers to impaired coordination of voluntary muscle movement. "From the literature review, among 173 patients with NEFL mutations, ataxia was found in 22 patients and cerebellar atrophy in 4 patients." (PMID 34768465, 2021). "According to the literature review, in 173 patients with NEFL mutations, ataxia was found in 22 patients and cerebellar atrophy in 4 patients." (PMID 34768465, 2021). "In particular, the frequency of the cerebellar ataxia was high in patients with NEFL mutations (72.7%), compared to GJB1 mutations (9.1%), PMP22 duplication (0%), and MFN2 mutations (0%)." (PMID 34768465, 2021). "Interestingly, we observed significant volumetric changes in the cerebella of CMT patients, especially with NEFL mutations, which were associated with the presence of cerebellar ataxia in this genetic subgroup." (PMID 34768465, 2021). "Antibodies targeting neurofilament light chain (NfL) have been reported as markers of ataxia and encephalopathy accompanying various cancers, especially neuroendocrine lineage neoplasms." (PMID 34659082, 2021). "When her severe ataxia progressed, neuroinflammation was characterized by high cerebrospinal fluid Purkinje cell cytoplasmic antibody type 1 titers, oligoclonal bands, and neurofilament light chain." (PMID 30288393, 2018). "We searched Medline and ISI Web of Science for reports published before Mar 31, 2025, with the search terms [“spinocerebellar ataxia” AND “biomarker” OR “neurofilament light chain (NfL)” OR “MRI“ OR “digital outcome“ AND “prospective“ AND “electrophysiological” OR “follow-up“ OR “longitudinal“]." (PMID 40411538, 2025). "Handgrip strength (HGS) may be considered as a biomarker to predict the progress of SCA3 and align with the alteration of plasma neurofilament light chain (NfL) and Scale for the Assessment and Rating of Ataxia (SARA)." (PMID 37817286, 2023). "Moreover, Trim2-deficient mice showed an accumulation of neurofilament light chain (NEFL) in neuronal structures, which causes axonopathy, progressive neurodegeneration, and juvenile onset of tremor and ataxia." (PMID 32698497, 2020). "In addition, cerebellar ataxia, which is commonly manifested in patients with NEFL mutations, is not well observed in the other genetic mutations, such as PMP22 and MFN2, except in 1 out of 11 patients with GJB1 mutations." (PMID 34768465, 2021).
multiple system atrophy (27 papers, 2013 to 2025). Multiple system atrophy (MSA) is a neurodegenerative disorder characterized by autonomic failure (cardiovascular and/or urinary), parkinsonism, cerebellar impairment and corticospinal signs with a median survival of 6-9 years. "For example, MRI-based midbrain-to-pons (M/P) ratios below 0.52 and elevated levels of plasma or CSF neurofilament light chain (NfL) can help distinguish PSP from PD and multiple system atrophy (MSA), even in early or clinically ambiguous cases." (PMID 41405696, 2025). "Moreover, lower CSF levels of neurofilament light chain, t-tau, YKL-40, and C-reactive protein were found in PD patients compared to those with multiple system atrophy." (PMID 36446820, 2022).
polyneuropathy (27 papers, 2013 to 2026). A disease or disorder affecting more than one nerve. "Recent evidence suggests that both serum neurofilament light chain (sNfL) levels and small fiber related diagnostic variables may be valuable disease biomarkers of hereditary transthyretin amyloidosis with polyneuropathy (ATTRv-PN)." (PMID 38700599, 2024). "Background/Objectives: Serum neurofilament light chain (sNfL) is an early and sensitive biomarker of polyneuropathy." (PMID 41753271, 2026). "During the APOLLO study, proteomic analysis of patients with hATTR and polyneuropathy identified a new biomarker: the neurofilament light chain (NfL)." (PMID 40722719, 2025). "Recent research shows that the neurofilament light chain (NfL), a neuron specific cytoskeletal protein released into the blood and cerebrospinal fluid during axonal damage, correlates with polyneuropathy and disease severity in systemic amyloidosis." (PMID 38612579, 2024). "Of interest, serum neurofilament light chain has been recently studied in ATTRv; however, there are only preliminary results available, that show a correlation with the severity of polyneuropathy, thus proposing NfL as a biomarker for nerve damage." (PMID 35295833, 2022). "Genetic testing was performed according to polyneuropathy type; demyelinating/mixed: PMP22 duplication, MPZ, EGR2, LITAF, NEFL, PMP22, GJB1, axonal: MFN2, MPZ, NEFL, and GJB1." (PMID 24053775, 2013).
vascular dementia (27 papers, 2005 to 2025). A degenerative vascular disorder affecting the brain. "A part of the axonal cytoskeleton protein complex, neurofilament light chain (NF-L) has been suggested as a pathological hallmark in various neurological disorders, including hemorrhagic stroke, vascular dementia, and cerebral small vessel disease." (PMID 35368870, 2022). "Neurofilament light chain (NfL), a marker of axonal damage, was found to increase early in the CSF in SVD, even in non-disabled patients with white matter changes, and in MCI patients who later developed vascular dementia." (PMID 34066951, 2021).
dementia with Lewy bodies (25 papers, 2013 to 2025). "Neurofilament light chain (NfL) may be useful in the differentiation of behavioral variant FTD from primary psychiatric disorders (PPDs) or dementia with Lewy bodies (DLB)." (PMID 39519389, 2024).
injury (24 papers, 2012 to 2025). Damage inflicted on the body as the direct or indirect result of an external force, with or without disruption of structural continuity. "Traditional protein biomarkers, including S100B, GFAP, UCH-L1, neurofilament light chain (NF-L), and tau, were initially markers for acute brain injury, but their role in chronic PCS is less clear due to inconsistent long-term elevation and limited correlation with symptom severity." (PMID 40722345, 2025).
encephalitis (23 papers, 2019 to 2026). An acute inflammatory process affecting the brain parenchyma. "Our previous study revealed considerably elevated serum neurofilament light chain in convalescent patients with anti-NMDAR encephalitis, suggesting persistent neuroaxonal injury during the recovery phase." (PMID 40440891, 2025). "Herein, we describe two cases of antibody negative ICI-mediated encephalitis with elevated serum Neurofilament light chain (sNfL) levels." (PMID 38860018, 2024). "Neurofilament light chain (NF-L) drastically increases in CNS during asymptomatic and chronic stages of infection in animals that develop encephalitis, and drops in animals that do not, showing increased neuroaxonal damage in animals that develop encephalitis." (PMID 34451482, 2021).
chronic kidney disease (20 papers, 2022 to 2026). Impairment of the renal function secondary to chronic kidney damage persisting for three or more months. "Associations between serum levels of neurofilament light chain and chronic kidney disease, as well as indicators of renal function across various subgroups." (PMID 39581996, 2024). "Associations between serum neurofilament light chain levels and chronic kidney disease in NHANES 2013–2014." (PMID 39581996, 2024). "The relationships of serum neurofilament light chain (NfL) levels with chronic kidney disease (CKD) and renal function indicators remain controversial, and comprehensive studies with large sample sizes are lacking." (PMID 39581996, 2024).
cerebral small vessel disease (19 papers, 2020 to 2026). Cerebral small vessel disease is the term currently used to pathological processes that affect the brain parenchymal circulation (arterioles, capillaries, and veins). "Neurofilament light chain (NfL) and glial fibrillary acidic protein (GFAP) have emerged as biomarkers for cerebral small vessel disease (SVD)." (PMID 38581544, 2024).
cortical atrophy (18 papers, 2018 to 2026). "Presymptomatic C9ORF72 repeat expansion carriers exhibit neuroimaging evidence of cortical atrophy and elevation of the plasma biomarker neurofilament light chain (NfL), occurring possibly as early as 30 years prior to disease onset." (PMID 40140908, 2025).
relapsing-remitting multiple sclerosis (18 papers, 2016 to 2026). The most common clinical variant of multiple sclerosis, characterized by recurrent acute exacerbations of neurologic dysfunction followed by partial or complete recovery. "Neurofilament light chain (NFL) in CSF correlates with long-term prognosis in MS, is a risk factor for conversion from clinically isolated syndrome (CIS) to relapsing remitting multiple sclerosis (RRMS), and decreases on treatment with fingolimod and natalizumab." (PMID 30021640, 2018).
Charcot-Marie-Tooth disease (17 papers, 2008 to 2025). "In this review, we will focus on Charcot-Marie-Tooth (CMT) disease, for which NEFL and NEFH are causal genes." (PMID 38164457, 2023). "Third, mutation of NEFL has traditionally been recognized as a cause of Charcot-Marie-Tooth disease, congenital myopathy in humans, and motor neuron disease in mice." (PMID 34511133, 2021). "Here, we demonstrate that allele-specific CRISPR gene editing in a human model of axonal Charcot-Marie-Tooth (CMT) disease rescues pathology caused by a dominant missense mutation in the neurofilament light chain gene (NEFL, CMT type 2E)." (PMID 34485306, 2021). "Of these, a single mutation in the gene NEFL was identified in all affected family members, (c.1261C > T; p.R421X associated with truncated NEFL protein levels) which has previously been associated with Charcot-Marie-Tooth disease." (PMID 32345347, 2020). "Regarding its functions, NfL is known to support the radial expansion of large myelinated axons, which explains mutations in the NEFL gene resulting in nerve damage as in Charcot-Marie-Tooth disease." (PMID 38503931, 2024).
synucleinopathies (17 papers, 2017 to 2026). "When combined with other biomarkers—such as neurofilament light chain, amyloid, tau, and glial fibrillary acidic protein—and applied to diverse biological samples, these assays can significantly improve the diagnostic precision for synucleinopathies." (PMID 39574205, 2024). "In this study, we analyzed the concentration of potential marker protein candidates, such as neurofilament light chain (NfL), glial fibrillary acidic protein (GFAP), a-Syn, and total tau (tau) in patients with different types of alpha-synucleinopathies." (PMID 34630068, 2021).
chronic inflammatory demyelinating polyneuropathy (16 papers, 2018 to 2026). "In current retrospective longitudinal study, we utilized logistic regression models to investigate the associations of serum neurofilament light chain levels with 1-year disease progression and therapy response during follow-up in chronic inflammatory demyelinating polyneuropathy." (PMID 33796853, 2021). "In chronic inflammatory demyelinating polyneuropathy, serum neurofilament light chain (NfL) has emerged as a promising biomarker, correlating with disease activity and treatment response." (PMID 41373880, 2025). "Serum neurofilament light chain (sNfL) levels were assayed in patients with newly diagnosed chronic inflammatory demyelinating polyneuropathy (CIDP)." (PMID 33617139, 2021). "Hence, our findings warrant further prospective research regarding the value of neurofilament light chain as potential prognostic biomarker in chronic inflammatory demyelinating polyneuropathy." (PMID 33796853, 2021).
motor neuron disease (16 papers, 2018 to 2025). "Phosphorylated neurofilament heavy chain (pNfH) and neurofilament light chain (NfL) have been reproducibly associated with axonal degeneration, and levels of these biomarkers tend to increase in both cerebrospinal fluid (CSF) and plasma/serum of patients affected by motor neuron diseases (MNDs)." (PMID 32032473, 2020). "Both neurofilament light chains (NfL) and phosphorylated neurofilament heavy chains (pNfH) can be measured in serum and in CSF and have been shown to be correlated with disease severity and survival parameters in motor neuron disease." (PMID 34064596, 2021).
Obesity (16 papers, 2020 to 2026). Accumulation of substantial excess body fat. "Glial fibrillary acidic protein (GFAP)/neurofilament light chain (NfL) may serve as monitoring tools for cognitive risk in T2D/obesity." (PMID 40842786, 2025). "Apart from CGRP, there are other peptides that have been studied to be influenced by age and sex such as the neuropeptide Y, which is also elevated in unhealthy obesity, or the neurofilament light chain, which should be adjusted by age when studying its levels." (PMID 41155252, 2025).